BUB1B (BUB1 mitotic checkpoint serine/threonine kinase B)
Diseases named in the same sentence as BUB1B in open-access papers (continued):
Sharing a sentence is not in itself a finding about the gene and the disease.
seminoma (1 paper, 2010). A radiosensitive malignant germ cell tumor found in the testis (especially undescended), and extragonadal sites (anterior mediastinum and pineal gland). "In seminomas, BUB1B expression was similar to that of normal testis, and significantly higher compared to the non-seminomas (P<0.001)." (PMID 20411023, 2010). "The level of BUB1B was significantly decreased in non-seminomas (P<0.001)." (PMID 20411023, 2010). "BUB1B expression was significantly reduced in non-seminomas compared to normal testis (P<0.001)." (PMID 20411023, 2010).
serous ovarian cancer (1 paper, 2024). "The findings showed that high expression levels of BUB1B, BUB3, or TTK were associated with better survival rates in serous ovarian cancer patients treated with paclitaxel compared to patients with low expression levels." (PMID 38987356, 2024).
uterine carcinosarcoma (1 paper, 2025). A usually aggressive malignant neoplasm arising from the uterine corpus and less often the cervix. "BUB1B alterations were identified in 32 cancer types, with uterine carcinosarcoma exhibiting the highest frequency at 7.02%." (PMID 40076684, 2025).
cancer (163 papers, 2005 to 2026). A tumor composed of atypical neoplastic, often pleomorphic cells that invade other tissues. "Research has demonstrated that the overexpression of BUB1B is associated with unfavorable prognoses in various cancer patients, indicating its potential significance in tumor metastasis and treatment resistance." (PMID 40076684, 2025). "Collectively, the mechanisms underlying the effects of BUB1B in cancer remain incompletely understood." (PMID 41163302, 2025). "BUB1B is overexpressed or mutated in many cancers and contributes to chromosomal instability, aneuploidy, and tumorigenesis." (PMID 41439111, 2025). "This study found that BUB1B was upregulated in most cancers and was significantly linked to patient prognosis." (PMID 40076684, 2025). "Approximately 2% of cancer patients have BUB1B gene mutations; the main types were deletion mutations, profound deletions and amplifications." (PMID 39048649, 2024). "Rare BUB1B variants were found in ~ 1.9% of the early-onset/familial PrCa cases and in ~ 0.6% of other cancer patients fulfilling criteria for hereditary disease." (PMID 39014450, 2024). "BUB1 was associated with overall survival (OS) in eight cancers and disease-free survival in ten; BUB1B was associated with OS in nine cancers and DFS in eleven." (PMID 39048649, 2024). "In vitro, decreased BUB1B in C1 and C2 clones led to significantly increased proliferation rates compared with WT cells, supporting the oncogenic cancer-predisposing role of this variant." (PMID 39014450, 2024). "BUB1 was negatively correlated and BUB1B was positively correlated with cancer-associated fibroblasts and endothelial cell infiltration." (PMID 39048649, 2024). "Pan-cancer analysis revealed that high expression of BUB1 and BUB1B was associated with poor prognosis and associated with immune infiltration in various cancers." (PMID 39048649, 2024). "High BUB1B expression was associated with OS in nine cancers, including ACC and KIRC and DFS in 11 cancers, including ACC, CHOL and KIRC." (PMID 39048649, 2024). "We used TIMER, CBERSORT, TIDE, XCELL, MCPCOUNTER, and QUANTISEQEPIC databases to explore the correlation between BUB1and BUB1B and cancer-associated fibroblast (CAF), endothelial cell and neutrophil infiltration levels in different tumors in TCGA database." (PMID 39048649, 2024). "The BUB1B gene plays a vital role in encoding a kinase which is involved in the spindle checkpoint function, resulting in many cancer forms." (PMID 36980449, 2023). "On the basis of these results, we investigated the implications of differential BUB1B expression on prognosis, tumor immunity, and gene mutation in pan-cancer." (PMID 37055476, 2023). "Mutation frequencies of the SAC genes remained low, and only rare polymorphisms in MAD1L1, MAD2L1, and BUB1b were found in certain cancers involved in the modulation of the cell cycle arrest." (PMID 37007941, 2023). "Analysis of TCGA data revealed overexpression of BUB1B compared to normal in most cancers and overexpression was associated with poor prognosis." (PMID 35847923, 2022). "We extended the overall survival analysis of BUB1B in other solid tumors in TCGA and found that high expression of BUB1B is associated with poor overall survival in most cancer types." (PMID 35847923, 2022). "BUB1B encodes a kinase involved in spindle checkpoint function, whose impairment is associated with various cancers." (PMID 35774795, 2022). "We further confirmed that higher BUB1B/BUBR1-expression level is consistently associated with poor clinical outcomes in various cancers." (PMID 34545188, 2021). "The reduction of BUB1B level or inhibition of BUB1B kinase activity in human cancer cells resulted in massive chromosome loss and apoptotic cell death." (PMID 33431813, 2021). "Mitotic checkpoint serine/threonine kinase B (BUB1B), the mammalian homolog of yeast Mad 3, is susceptible to cancer and causes chromosome loss and apoptotic cell death in human cancer cells." (PMID 31987036, 2020).
cancer (continued). "BUB1 mitotic checkpoint serine/threonine kinase (BUB1), BUB1 mitotic checkpoint serine/threonine kinase B (BUB1B), both of them play a central role in mitosis which are reported associated with aneuploidy and several forms of cancer." (PMID 33408743, 2020). "Deleterious mutations in BUB1B are associated with premature chromatid separation, which can lead to increased susceptibility to cancer as well as to producing autosomal trisomy offspring, or other issues in conception." (PMID 29641532, 2018). "As a checkpoint for proper chromosome segregation and preventing separation of the duplicated chromosomes in normal cells, the role of BUB1B (encoding BUBR1) in cancer cells is still controversial." (PMID 30363964, 2018). "The contradiction of BUB1B, between its role in suppressing cancer and upregulating cancers, is demonstrated in varying reports of cancer-associated missense and nonsense mutations in BUB1B, in several cancers." (PMID 30100882, 2018). "BUB1B is linked to malignant cancer traits, such as metastasis, proliferation, and cell apoptosis." (PMID 41163302, 2025). "We analyzed BUB1B mutations in 32 cancer types using TCGA data." (PMID 40076684, 2025). "Currently, BUB1B mutations are underreported in these cancers." (PMID 40076684, 2025). "Mutations in BUB1 and BUB1B genes have been identified in cancer." (PMID 39048649, 2024). "CCNA2, TTK, TOP2A, AURKA, AURKB and BUB1B are also closely associated with cancer." (PMID 39537209, 2024). "Our study shows that different BUB1B variants may uncover a trigger for CIN-driven carcinogenesis, supporting the role of BUB1B as a (pan)-cancer predisposing gene with potential impact on genetic counseling and treatment decision-making." (PMID 39014450, 2024). "BUB1 Mitotic Checkpoint Serine/Threonine Kinase B (BUB1B) is an essential component of the mitotic checkpoint, and its high expression is thought to be associated with the progression and recurrence of several cancers." (PMID 35677427, 2022). "Additionally, among 33 cancer types, BUB1B higher expression caused a worse overall survival and shorter progression-free survival time in one-third of types (all HR>1, all P<0.05)." (PMID 35517426, 2022). "In addition to aberrant expression, mutation of BUB1B can cause aneuploidy, thus affecting cancer development." (PMID 35517426, 2022). "Furthermore, lowering BUB1B levels or inhibiting BUB1B kinase activity in human cancer cells causes significant chromosomal loss and apoptotic cell death." (PMID 35847923, 2022). "The overexpression of BUB1B may be involved in impaired spindle checkpoint function, which is linked to different cancers." (PMID 34616422, 2021). "Moreover, reduction of BUB1B level or inhibition of BUB1B kinase activity in human cancer cells resulted in massive chromosome loss and apoptotic cell death." (PMID 33431813, 2021). "BUB1B is associated with DNA repair and known to drive the development of cancer." (PMID 29596435, 2018). "Germline mutations in the BUB1B gene encoding BubR1 cause premature chromatid separation and lead to the mosaic variegated aneuploidy syndrome, which is characterized by constitutional aneuploidy and a high risk of childhood cancers." (PMID 28410192, 2017). "In addition, mutations that reduce BUB1B expression in humans lead to cancer-susceptible mosaic variegated aneuploidy syndrome." (PMID 26000094, 2015). "Thus, BUB1B is a candidate tumor suppressor gene in the esophagus whose downregulation in normal esophageal tissue is associated with cancer development." (PMID 18425214, 2007). "Furthermore, BUB1B mutations and abnormal expression can contribute to the development of cancer." (PMID 36185088, 2022). "In this study, bioinformatics methods were used to elucidate the expression pattern, prognostic significance and potential function of BUB1B in various cancer types." (PMID 40076684, 2025).
cancer (continued). "Recent studies have increasingly demonstrated a correlation between elevated BUB1B expression and the incidence and progression of various cancers." (PMID 40076684, 2025). "Considering the essential function of BUB1B in mitotic checkpoint signaling and chromosome congression, abnormal BUB1B function results in diseases such as various cancers." (PMID 41163302, 2025). "Experiments have shown that BUB1 and BUB1B can promote cancer cell proliferation and are promising therapeutic targets 23-25." (PMID 40657363, 2025). "We investigated BUB1B’s role in pan-cancer using TCGA data, analyzing it with platforms like HPA, TIMER, TISIDB, GEPIA, cBioPortal, GDC, LinkedOmics, and CancerSEA." (PMID 40076684, 2025). "As a unit of SAC, BUB1B plays an essential role in mitosis, effectively preventing aneuploidy, which is a common feature of cancer." (PMID 41163302, 2025). "The top 200 linear model genes were screened against the known cancer driver genes in Cancer Gene Census, yielding four hits: BUB1B, EBF1, PPARG, and RECQL4." (PMID 41048341, 2025). "BUB1 mitotic checkpoint serine/threonine kinase B (BUB1B) has been found to participate in cancer progression." (PMID 41163302, 2025). "The results show that BUB1B was not only involved in the function of cancer, but also involved in inflammation and immunity." (PMID 40076684, 2025). "To further explore the relationship between BUB1B expression and cancer prognosis, we conducted a survival analysis across 33 cancer types utilizing overall survival (OS) as the metric." (PMID 40076684, 2025). "In this study, we conducted a comprehensive analysis to assess the potential utility of BUB1B in relation to cancer pathological staging and prognosis." (PMID 40076684, 2025). "Abnormal BUB1B expression has been reported in cancer development, progression, immune resistance, chemoresistance, and radioresistance." (PMID 41163302, 2025). "The findings demonstrate a significant upregulation of BUB1B expression across multiple cancer types, suggesting its potential as a crucial biomarker for cancer diagnosis and therapeutic targeting." (PMID 40076684, 2025). "BUB1 and BUB1B expressions were significantly higher in EC in all cancer stages (P < 0.01), with higher expression in middle to late stage cancer than early-stage cancer." (PMID 39048649, 2024). "A pan-cancer investigation of the BUB1B gene revealed its significant role in cancer, which is related to immunology, cancer stem cells, and genetic alterations in multiple cancer types." (PMID 39045407, 2024). "While BUB1b has been widely studied in various cancers, the potential role of BUB1b in ferroptosis is still elusive." (PMID 39043653, 2024). "MVA1 syndrome and the Premature Chromatid Separation (PCS) trait, caused by biallelic and monoallelic BUB1B variants, respectively, are the strongest evidence for a causal effect of CIN in cancer development arising from SAC defects." (PMID 39014450, 2024). "In our study, aside from the frameshift variant c.2481del and the splicing variant c.2009 + 1G > A, the BUB1B variants identified, both in HPC patients and in patients with other cancers, cluster at or near the TPR and B3BD domains (N-terminal)." (PMID 39014450, 2024). "BUB1 mitotic checkpoint serine/threonine kinase B (BUB1b) has been unequivocally identified as an oncogene in various cancers." (PMID 39043653, 2024). "IHC analysis revealed a significant increase in TTK and BUB1B expression in PDAC tissues compared to para-carcinoma tissues." (PMID 38711083, 2024). "Altered expression of SAC genes was observed in many solid tumors and knocking down BUB1B resulted in significantly increased cell death in LUAD cancer cells." (PMID 37228122, 2023). "Given the important roles of BUB1B in mitosis, the dysregulation of BUB1B is often found to result in aneuploidy and chromosomal instabilities, ultimately increasing the chances of cancer development." (PMID 37304238, 2023).
cancer (continued). "To further uncover the possible signaling pathways involved in BUB1B in pan-cancer, we first obtained the top one hundred most similar gene sets to BUB1B using GEPIA and performed enrichment analysis on this gene set." (PMID 37055476, 2023). "Using the TIMER method, it was revealed that BUB1B is significantly associated with B cell, CD8+ T cell, CD4+ T cell, macrophage, neutrophil, and DC infiltration levels in different cancers." (PMID 37055476, 2023). "Furthermore, in different cancer types, BUB1B demonstrated varying levels of connection with RNAss and DNAss (mainly positive association), implying that BUB1B may contribute to tumor progression by boosting cancer stemness." (PMID 37055476, 2023). "Given that, we further carried out a variety of pan-cancer analyses with BUB1B, including expression level analysis, immune cell infiltration, gene mutations, and so on." (PMID 37055476, 2023). "BUB1B has been reported to contribute to the initiation and development of several cancers.In this paper, We found that BUB1B is up-regulated in LUAD and a biomarker for prognosis outcome by bioinformatic analysis." (PMID 35068350, 2022). "Reduced expression of BUB1B or suppression of its kinase activity resulted in apoptotic cell death in cancer cells." (PMID 35847923, 2022). "BUB1B also showed a highly significant positive correlation with FOXM1 in all the TCGA cancer types." (PMID 35847923, 2022). "We further validated that ZNF143 knockdown had a similar effect on LUAD cancer cell proliferation, migration, and invasion as BUB1B knockdown, which was counteracted by BUB1B overexpression." (PMID 35068350, 2022). "BUB1 mitotic checkpoint serine/threonine kinase B (BUB1B) was found to be up-regulated in a variety of cancers, but only two previous study showed that BUB1B was overexpressed in NPC and the sample size was small." (PMID 36577966, 2022). "The previous study has indicated the significant prognostic value of combined expression of BUB1B with several genes in human cancers; this study also explored the combined prognostic value of BUB1B with important genes in THCA." (PMID 35517426, 2022). "At present, many studies have shown that the hub genes CDC20, CDK1, BUB1, CCNB1, and BUB1B identified in our PPI network are involved in cancer progression." (PMID 35664322, 2022). "This study suggests that the crosstalk between FOXM1 and BUB1B plays an essential role in the growth and survival of cancer cells." (PMID 35847923, 2022). "An impairment in BUB1B often leads to aneuploidy and chromosome instability, which can contribute to an increased cancer incidence." (PMID 36185088, 2022). "It was found that the correlation of BUB1B and hsa-miR-130a-3p coexpression was significant in multiple cancer types, especially in ACC, BLCA, COAD, KICH, PRAD, and READ." (PMID 36185088, 2022). "Both BUB1 and BUB1B genes were identified as shared ceRNAs across more than two HD cancers of interest." (PMID 35757968, 2022). "These researches have presented the vital prognostic value of BUB1B in human cancers and revealed its potential as a useful therapeutic target." (PMID 35517426, 2022). "Pathogenic variants in five “other” cancer predisposition genes (ALK, BUB1B, FANCG, RB1 and XPC) exclusively investigated for truncating variants, were identified in seven patients." (PMID 35039564, 2022). "There have been several studies that have focused on transcriptional activation of BUB1B/BUBR1 in cancers." (PMID 34545188, 2021). "The roles of BUB1/BUB1B in cancer cells are still controversial with contradicting results from studies." (PMID 33872216, 2021). "Overexpression of CDK1, MCM2, E2F2, PLK1, CCNB1/2, BUB1, BUB1B, CDC25 has been associated with aberrant proliferation in many cancer types including HCC." (PMID 33499054, 2021). "As a characteristic cancer-promoting factor, BUB1B promoted proliferation and invasiveness both in vivo and in vitro." (PMID 33431813, 2021).